MMP9 (matrix metallopeptidase 9)
Diseases named in the same sentence as MMP9 in open-access papers (continued):
Sharing a sentence is not in itself a finding about the gene and the disease.
tumor (continued). "However, immunostaining showed no relevant difference in the expression of gelatinases (MMP-2 and MMP-9) between the three types of tumour (not shown)." (PMID 11875720, 2002). "In addition, whether other metalloproteinases are also regulated by HIF-1α to mediate the immune escape of tumor cells from the killing by NK cells, and whether common metalloproteinases (MMP2, MMP9, and ADAM10) are also regulated by factors parallel to HIF-1α, still require further research." (PMID 40563539, 2025). "In addition, it inhibits metastasis by downregulating the metalloproteinases MMP-2 and MMP-9, essential in the degradation of the extracellular matrix, and by disrupting the CXCL12/CXCR4 chemokine axis involved in the epithelial–mesenchymal transition and tumor cell migration." (PMID 40572668, 2025). "However, despite this positive association, evidence suggests that NK cells can undergo alterations within the tumor milieu, including the upregulation of inhibitory receptors and the expression of VEGF and matrix metalloproteinase 9 (MMP9), which may compromise their anti-tumor efficacy." (PMID 40136347, 2025). "Furthermore, when TRAF4 was knocked out, OA could no longer inhibit the expression of SOX2, Olig2, and MMP9, nor did it impair tumor sphere formation." (PMID 39716976, 2025). "There are no studies investigating how somatic inactivation of BRCA1 would be related to increased MMP9 expression; however, a hypothetical explanation would be that genomic instability resulting from BRCA1 inactivation may induce an inflammatory response within the tumor microenvironment." (PMID 40870889, 2025). "Within the tumor vascular microenvironment, high expression of MMP-9 promotes pathological angiogenesis, regulated upstream by Runx2, which when transcriptionally inactive may weaken MMP-9 expression, thus inhibiting pathological angiogenesis and maintaining normal blood shear stress." (PMID 40821116, 2025). "To explore whether MMP9 could distinguish adherent from nonadherent tumors in an independent contemporary cohort, we prospectively enrolled 45 VS patients and established primary tumor cultures." (PMID 38887507, 2024). "While adherent tumors may be larger than nonadherent tumors overall, in a size-matched sub-analysis of adherent and nonadherent tumors (n = 5 per group, tumor diameter 2.7 vs 2.7 cm), adherent VS still secreted higher levels of MMP9 (87.4 vs 2.6 ng/ml, P = .012)." (PMID 38887507, 2024). "Additionally, the immunohistochemical analysis indicated reduced expression of Ki67, MMP9, Cyclin D1, and CDK4 in the tumor tissues of CMHE-treated mice, implying the repression of the proliferative and metastatic ability of cancer cells in the tumor tissues by CMHE treatment." (PMID 39161904, 2024). "Furthermore, we found that DOKD inhibited CT26+ tumor cell growth by regulating inflammation, metastasis, and angiogenesis by activating the IL-17/TLR4/NF-κB p65 pathway and inhibiting the activation of the Src/HIF-1α/Erk1/2/Snail/N-cadherin/Vimentin/MMP9 and Erk1/2/HIF-1α/STAT3/VEGFA pathways." (PMID 37239383, 2023). "Acidic tumour environment due to the increasing rate of glycolysis, however, might trigger the secretion of Cathepsin K as a member of lysosomal cysteine cathepsin (LCC) subgroup, which competed to disrupt cysteine interaction with zinc in proMMP-9, resulting in active MMP-9 production." (PMID 37600570, 2023). "Interestingly, MMP-2 and MMP-9 can bind to low-density lipoprotein receptor-related protein 1 (LRP1), activate ERK, inhibit the JNK pathway, facilitate tight adhesion of tumor cells to the stroma, and induce tumor cell invasion into blood vessels and lymphatic vessels." (PMID 37359527, 2023). "However, a single study indicates that MMP-9 expression is not dependent on the mean tumor microvascular density or any clinical parameters of the lesion; nevertheless, in our opinion, MMP-9 shows preliminary potential as a marker of poor prognosis in OS patients." (PMID 38138968, 2023).
tumor (continued). "This may be associated with the activation of an altered pathway of signal transduction by laminin-1 through a 67 kDa nonintegrin receptor of laminin or integrins on tumor cells, which results in basement membrane dissolution with collagenolysis by MMP-9 while normal tissue is becoming neoplastic." (PMID 36945954, 2023). "Additionally, Wnt-1, β-catenin, cyclin-D1, MMP2, and MMP9 as well as Ki-67 levels were higher in tumor cells of the model + sh-SOST group than that of the model + sh-NC group, demonstrating that SOST suppression was capable of activating Wnt/β-catenin signaling in ocular orthotopic tumor models." (PMID 35785219, 2022). "Likewise, MMP-9 is secreted mainly by tumor-associated macrophages (TAMs), not BCC tumor cells." (PMID 35572966, 2022). "Thus, the tumor-promotive function of KDELR2 on MMP2 and MMP9 might be tissue/cell-specific." (PMID 36096734, 2022). "In immune analysis, ICAM1, IL1B, IL-6, MMP1, MMP3, MMP9, and SERPINE1 all showed positive correlations with most immune cells, implying that CC and MF may exert an antitumor activity by interacting with these genes and immune cells, and thus control tumor development." (PMID 35783510, 2022). "However, a deficiency of endogenous IFN‐β may allow neutrophils to express higher levels of C‐X‐C chemokine receptor type 4 (CXCR4), vascular endothelial growth factor (VEGF), and matrix metalloproteinase 9 (MMP9), thus promoting angiogenesis, mobility, and tumor homing." (PMID 35612789, 2022). "However, plasma MMP9 was not correlated with tumor size, invasive pattern, or angiogenesis." (PMID 34980260, 2022). "ATO may reduce various tumor cell activities, inhibit cell attachment to peritoneal mesothelial cells, enhance the interaction between tumor cells, downregulate the expression level of matrix metalloproteinase (MMP)-2 and MMP-9, and upregulate the expression level of MMP inhibitor (TIMP)." (PMID 36090905, 2022). "In addition to regulating ECM organization, MMP9 degradation of non-matrix substrates such as chemokines, growth factors or integrins contributes to the control of signals promoting migration of both tumor and stromal cells." (PMID 33572115, 2021). "In addition, expression of molecules involved in ECM remodeling such as several metalloproteinases (MMP2, MMP9, MMP10 and MMP13), serine protease (PLAU) collagens, fibronectins and integrins indicate that functional EMT transition and metastasis take place within the tumor microenvironment." (PMID 34946170, 2021). "As expected, in untreated mice bearing T1525 tumors immunohistochemistry and immunofluorescence showed strong MMP9 production by infiltrating MCs and not by T1525 tumor cells, whereas in T23 tumors MMP9 was mild and diffusely expressed by tumor cells and no infiltrating MCs were detected." (PMID 33737929, 2021). "Moreover, studies have reported that tumor constituent cells regulate the biomechanical properties of the ECM, decreases the ECM stiffness by increasing the matrix metalloproteinase (MMPs) such as MMP2, MMP9, MMP13, and MMP14 enabling them to metastasize to distant tissues." (PMID 34613483, 2021). "Tumor-derived EVs deliver ECM-MMPs inducers which can contribute to matrix degradation in different diseases: For instance, EVs derived from ovarian cancer contain high levels of MMP-2, MMP-9, and urokinase-type plasminogen activator proteinases that could degrade the ECM104." (PMID 34446834, 2021). "Intravenously injected bacteria could selectively accumulate in tumor site and temporally express GFP and cardiac peptides in response to hypoxia, enhancing survival rate of tumor bearing mice, suppressing tumor growth rate and expression of MMP-9, VEGFR2, CD31 and Ki67 biomarkers." (PMID 34344421, 2021).
tumor (continued). "Thus, high-grade tumor budding and expression by MICs of MMP-9, -11, -14, TIMP-1, or TIMP-2 were associated with a poor prognosis in all cases, whereas the association of low tumor budding count and the non-expression of either MMPs or TIMPs was associated with a better outcome." (PMID 33669393, 2021). "However, at the chosen dose of ara-C, the tumor burden could not be further reduced or survival prolonged when ara-C was combined with an MMP-9-inhibitor." (PMID 31919471, 2020). "In particular, Plasmodium infection can significantly decrease MMP-9 expression by regulating IGF-1, which might signal intracellularly through the PI3 and MAPK pathways after binding to IGF-1R on the cell surface and thereby increase the expression of MMPs in tumor-bearing mice." (PMID 32972437, 2020). "Results from clinical trials indicate that HIV-protease inhibitors are more efficacious in the early (premetastatic) stages of tumor progression; this observation suggests that the HIV-protease inhibitors could be explored for metastases prevention in early-stage cancers overexpressing MMP-9." (PMID 32630531, 2020). "Finally, other regulatory mechanisms of MMP-9 expression are mediated by MMP-9 allelic variation (rs3918251GG (A>G) and by the over-expression of SOX4 responsible for the concomitant up-regulation of MMP-2/9 and NF-κB/p65 and, consequently, for a more aggressive tumor phenotype." (PMID 32392801, 2020). "The expression of PCNA, VEGF, MMP‐2, and MMP‐9 in Diet I+NDEA and Diet II+NDEA groups was significantly lower than in the NDEA group (p < 0.01 or p < 0.05), indicating that Diet I and Diet II could inhibit cancer proliferation and affect tumor neovascularization, invasion, and metastasis." (PMID 30680188, 2019). "Additionally, in statistical analyses, MMP-2 in tumor-stroma (T-S), MMP-9 (T-S), TIMP-1 (T-S), and TIMP-2 (T-S) variables were introduced in order to determine the differences in the expression of metalloproteinases and their inhibitors between the tumor and stroma." (PMID 31223594, 2019). "Additionally, in our further study, it will be interesting to determine the individual roles of MMP-9, PDGFR-α, and PECAM-1 during lung metastasis as well as to learn whether the functions of MMP-9, PDGFR-α, or PECAM-1 are tumor-type or cancer cell-type specific." (PMID 30483898, 2019). "Therefore, we further emphasized our speculation that the concomitant up-regulation of MMP9 and THBS1 found in the LNCaP-MST cells may be due to MDM2 overexpression that can easily lead to the acquisition of aggressive tumor phenotype with increased metastatic potential." (PMID 29748481, 2018). "After inhibition of 3T3-A-EXO uptake by cytochalasin D, increased MMP9 activity in 3LL tumor cells could not be detected, suggesting that MMP3 in 3T3-A-EXO cannot directly induce MMP9 activation and fusion of 3T3-A-EXO and that 3LL tumor cells are required for this process." (PMID 29137230, 2017). "However, the expression levels of MMP-2 and MMP-9 did not change significantly in primary tumor." (PMID 28819116, 2017). "Thus, our studies uncovered a previously unappreciated role of tumor-fibroblast interactions in the stimulation of tumor angiogenesis, and an essential role of the MAPK-AP1 axis in the cooperative up-regulation of the angiogenic driver MMP9 by cytokine crosstalk." (PMID 28423685, 2017). "Moreover, the expression of LATS2 and p-YAP1(Ser127) increased, whereas YAP1, Axl, c-Myc, Cyr61, MMP-2 and MMP-9 expression levels were simultaneously decreased in amlexanox-treated group relative to the DMSO-treated group, which was consistent with the subcutaneous tumor tissues results." (PMID 29048430, 2017). "Moreover, stratified analysis based on sample types found that high MMP-9 expression in tissue specimen but not serum was significant correlated with advanced T category (RR = 0.81, 95% CI: 0.72-0.92), tumor stage (RR = 0.69, 95% CI: 0.60-0.80) and poor 5-year OS (1.33, 95% CI: 1.18-1.50)." (PMID 26918342, 2016).
tumor (continued). "EMT is considered as a major mechanism involved in the dissemination of tumor cells in HCC, However, our current data showed that ApoA-1 treatment might inhibit CTC formation via EMT-independent mechanism, in which the expressions of MMP2, MMP9, and VEGF were strongly down-regulated." (PMID 27683106, 2016). "Thus, while MMP-9 activity may regulate autocrine TGF-β activity in 4T1 cells, the enforced expression and activation of this extracellular protease was unable to circumvent the tumor suppressing functions of CST-Abl in aggressive TNBCs." (PMID 27626309, 2016). "Taken together with the results that depletion of neither TSG101 nor MMP-9 affected cell growth of HeLaS3 cells (data not shown), these results suggest that TSG101 may be implicated in the invasive potency of HeLaS3 cells as a tumor-enhancing gene." (PMID 26608825, 2015). "However, there is no common cut-off value for defining positive tumor MMP-9 expression in NSCLC." (PMID 25888323, 2015). "However, the roles of tumor and stromal MMP9 in this model were not wholly interchangeable; inhibition of stromal MMP9 (whether alone or in combination with tumor-derived MMP9) was necessary to achieve maximal reduction of metastatic burden." (PMID 25961845, 2015). "Moreover, HA–CD44 interaction may elevate oncolytic efficiency not only by activating Akt but also promote viral spread within GBC tissue by degrading collagen IV through MMP-9 secretion, finally converging to enhance the overall MYXV-mediated anti-tumor effect on GBCs in vivo." (PMID 24725816, 2014). "To conclude, the present study is the first report suggesting that evaluation of active MMP-9 by immunohistochemistry and the MMP-9 activation ratio by gelatin zymography may be a useful adjunct to known clinicopathological factors in predicting tumor behavior." (PMID 24778099, 2014). "Furthermore, the VEGF/gelatinase B/MMP-9 axis promotes hyperactive haematopoiesis, expanding myeloid-derived suppressors of T-lymphocyte proliferation and activation, which results in the repression tumour immune surveillance, which promotes tumour progression." (PMID 24473089, 2014). "Furthermore, the CD31 staining pattern showed that the vascular morphology also differed between the two groups; whereas control tumors possessed properly formed blood vessels with structured lumina, the MMP9 KD tumor vasculature was more disorganized and often lacked lumina." (PMID 24811362, 2014). "We previously reported the profiles of tumor infiltrating leukocytes in cutaneous angiosarcoma (AS) and suggested that a combination of docetaxel (DTX) with bisphosphonate risedronate sodium (RS) might be effective for MMP9-expressing AS by targeting immunosuppressive cells such as M2 macrophages." (PMID 24489574, 2013). "Double immunofluorescence analysis showed that a subpopulation of CD30+ cells overexpressed TGFβ1 and MMP9, suggesting that CD30+/TGFβ1+ and CD30+/MMP9+ cells may potentiate a metastatic environment that allows CD30+ HL tumor cells to exit the local tumor microenvironment." (PMID 23988031, 2013). "Additionally, CAs were shown to directly promote tumor cell migration, and tumor secretion of pro-angiogenic and pro invasion factors (e.g., Vascular endothelial growth factor (VEGF) and matrix metalloproteinases (MMP)-9/2), effects that were abolished by b-blockers." (PMID 21888867, 2011). "Similarly, while most studies implicate MMPs, e.g. MMP9, in pro-angiogenic and carcinogenic behaviors through VEGF, in others, VEGF proteolysis results in an angiogenic response that is uncoordinated and ineffective, leading to lower vessel density and decreased tumor growth." (PMID 21535871, 2011). "This illustrated that revascularisation after irradiation required extracellular matrix modelling of MMP-9 by cells in the bone marrow, although tumour growth without irradiation did not, suggesting that they may depend on different pathways for recruiting new vasculature." (PMID 21587260, 2011).
tumor (continued). "However, this difference was not seen between the two groups who had MMP-9 positive tumour." (PMID 17026740, 2006). "Thus, the efficacy of the chemotherapy may not be great for patients with a tumour positive for MMP-9." (PMID 17026740, 2006). "However, in the later stages of tumour development, as cells become refractory to growth inhibition, then the role of LAP in promoting αvβ6-dependent cell movement and MMP-9 expression may assume greater significance, and this may be one of the ways in which TGF-β promotes tumour development." (PMID 12373600, 2002). "FABP4 and vimentin expression was increased in proximity to the tumor, while caveolin-1, CD44, MMP9, and adiponectin showed minimal or no changes." (PMID 41596770, 2026). "Zymography data showed that MMP-2 and MMP-9 expression was down-regulated M13SV1-EGFP-Neo treated with minocycline, but not in HS578T-Hyg cells or M13HS-2 and M13HS-8 tumor hybrids." (PMID 40471394, 2025). "The paired sample comparison graph demonstrated that the expression levels of ILF3, MMP9, MMP10, MMP11, and MMP26 in PCa tumor tissue were elevated than adjacent non-tumor tissues (P < 0.05)." (PMID 40607407, 2025). "MMPs are zinc-dependent endopeptidases produced by both tumour and non-tumour cells within the tumour microenvironment, with MMP2 and MMP9 classified as gelatinases." (PMID 40259907, 2025). "Up to 88% reduction in tumor volume with human MMP-2 oligopeptide; 80% reduction with one of the human MMP-9 oligopeptides; no pronounced side effects." (PMID 39594665, 2024). "Our in vivo analysis of orthotopic tumours with picrosirius red staining also revealed a decrease in the ECM, and inhibiting MMP2 or MMP9 alone was not as effective as the MET inhibitor or GW." (PMID 39025845, 2024). "A small number of MMP13+ cells were localized to the front lines where infiltrating immune cells attacked tumor cells, but neither MMP3+ nor MMP9+ cells were localized." (PMID 38774209, 2024). "To specifically compare MMP9 expression around the tumor vasculature in adherent and nonadherent tumors, we identified regions containing CD31 + vessels and queried the colocalization of MMP9 expression on consecutive histological sections." (PMID 38887507, 2024). "Compared to non-treated mouse tumours, macrophages in CT-treated tumours showed significant upregulation of phagocytosis genes such as Stab1, Mrc1, Mertk and downregulation of ECM and angiogenesis such as Mmp9 and Col1a1." (PMID 39578450, 2024). "Since we had already identified BMSCs as being responsible for MMP-9 expression, we did not expect any change in MMP-9 promoter activity in the tumor cells." (PMID 36674806, 2023). "3D mono-cultured BMSC spheroids secrete merely the inactive pro-enzyme of MMP-2 (66 kDa) and no MMP-9, whereas mono-culture tumor spheroids show very little or no expression and secretion of MMP-2 and MMP-9." (PMID 36674806, 2023). "When correlating MMP-1, MMP-2, MMP-9, TIMP-1, and TIMP-2 expression in tumor tissue in non-invasive and invasive PTC, we report significant positive correlation between TIMP-2 and MMP-2 in the non-invasive tumor group (rho = 0.378, p = 0.039)." (PMID 36551933, 2022). "The opposite relationship was observed in the tumor biomarkers a-SMA and MMP-9 even though it was not statistically significant." (PMID 36242015, 2022). "And the mRNA expression of MMP9 and SLC16A3 was significantly negative related to tumor purity (PTBP1, r = − 0.53; SLC39A1: r = − 0.58; P < 0.05)." (PMID 36307882, 2022). "Heparanase, MMP9, vimentin, and VEGF-B protein levels, were studied in both tumor and non-tumor adjacent tissues of all stages from CRC patients." (PMID 36139645, 2022). "Meanwhile, MMP9 and SLC16A3, the negative prognostic factors overexpressed in GBM, were identified as tumor-specific antigens for GBM patients." (PMID 36307882, 2022). "The expression of the tumor biomarkers Col1, Col4, a-SMA, and MMP-9 in this cohort of small PTCs differed significantly from normal thyroid tissue." (PMID 36242015, 2022).